TLR2 (toll like receptor 2)
Diseases named in the same sentence as TLR2 in open-access papers (continued):
Sharing a sentence is not in itself a finding about the gene and the disease.
sarcoidosis (14 papers, 2006 to 2025). Sarcoidosis is a multisystemic disorder of unknown cause characterized by the formation of immune granulomas in involved organs. "We genotyped 5 single-nucleotide polymorphisms (SNPs) in TLR2 and assessed the allelic diversity between 257 Japanese sarcoidosis patients and 193 Japanese healthy controls." (PMID 21437199, 2011). "The association between TLR2 polymorphisms and sarcoidosis needs to be confirmed by further replication studies, particularly in other ethnic groups." (PMID 21437199, 2011). "Indeed, polymorphisms in TLR2 loci have been shown in sarcoidosis and are also associated with disease course." (PMID 38165044, 2024). "Of these, TLR2 has been most frequently implicated in the pathogenesis of sarcoidosis." (PMID 36543347, 2022). "The current study was designed to determine whether TLR2 polymorphisms affect the development of sarcoidosis in the Japanese population." (PMID 21437199, 2011). "Our results indicate that a possible connection may exist between TLR2 polymorphisms and skin manifestations of sarcoidosis." (PMID 21437199, 2011). "TLR2 SNPs allele frequencies among sarcoidosis patients inflammatory sites and controls." (PMID 21437199, 2011). "It has been reported that polymorphisms in TLR2 might be important in a small group of Caucasian sarcoidosis patients." (PMID 21437199, 2011). "However, marginal associations were observed for TLR2 at rs3804099 and rs3804100 in sarcoidosis patients with cutaneous manifestations." (PMID 21437199, 2011). "Further studies, especially in other ethnic populations, are required to elucidate what association there may be between sarcoidosis and TLR2." (PMID 21437199, 2011). "Allele frequencies of SNPs of TLR2 among sarcoidosis patients and controls." (PMID 21437199, 2011). "Bronchoalveolar lavage (BAL) cells from sarcoidosis patients produce more TNF-α and IL-6 in response to TLR2 agonists than healthy controls, while PBMCs from sarcoidosis patients had impaired TLR2 responses." (PMID 32256501, 2020). "Bronchoalveolar (BAL) lavage cells from patients with sarcoidosis and healthy controls were stimulated with ligands taken from TLR-2 and TLR-4." (PMID 33173621, 2020). "In skin biopsies from sarcoidosis patients a strong trend (p = 0.0539) towards increased TLR2 expression was observed." (PMID 33057074, 2020). "We showed that PBMCs from patients with sarcoidosis had a higher baseline mRNA expression of dectin-1, TLR2, TLR4 and MR (6-fold, 11-fold, 18-fold, and 4-fold, respectively)." (PMID 27688795, 2016). "We showed that PBMCs from patients with sarcoidosis had a higher mRNA expression of dectin-1, TLR2, TLR4 and MR at baseline." (PMID 27688795, 2016). "Our results demonstrated that PBMCs from patients with sarcoidosis had a higher in vitro baseline mRNA expression of dectin-1, TLR2, TLR4 and MR than healthy subjects." (PMID 27688795, 2016). "A role for TLR-2 in immune activation and granuloma formation in sarcoidosis is further supported by genetic and mouse studies." (PMID 24339826, 2013). "Lately, continuous TLR-2 ligation by macrophage-derived serum amyloid A has been suggested to contribute to persistent stimulation of the immune response in sarcoidosis." (PMID 24339826, 2013). "There was a significantly reduced TLR2 gene expression in sorted AMs from sarcoidosis patients compared to healthy subjects (p = 0.024)." (PMID 20813038, 2010). "This indicates the potential of TLR2 as a marker for predicting sarcoidosis activity." (PMID 39904950, 2025). "Additionally, the number of monocytes undergoing phagocytosis in the blood of sarcoidosis patients is heightened compared to control subjects, and circulating monocytes also display higher TLR2 and TLR4 expression." (PMID 32256501, 2020). "In summary, the minor allele frequencies of TLR2 do not appear to be significantly relevant to sarcoidosis in the Japanese population." (PMID 21437199, 2011).
sarcoidosis (continued). "Genotype frequencies of five SNPs of the TLR2 gene in sarcoidosis patients and controls." (PMID 21437199, 2011). "Our results suggest that TLR2 polymorphisms are not significantly related to the pathogenesis of sarcoidosis in the Japanese population." (PMID 21437199, 2011). "However, there was a reduced TLR2 mRNA expression in patients with Löfgren's syndrome, which may be of relevance for macrophage interactions with a postulated sarcoidosis pathogen, and for the characteristics of the ensuing T cell response." (PMID 20813038, 2010). "TLR-2 and TLR-4 expression in blood mononuclear cells is significantly higher in patients with sarcoidosis than that in HCs." (PMID 41463010, 2025). "Bronchoalveolar lavage (BAL) cells from patients with sarcoidosis produce more TNF-α and IL-6 in response to TLR2 agonists compared to healthy controls, while PBMCs from sarcoidosis patients have impaired TLR2 responses." (PMID 32722050, 2020). "Baseline dectin-1, TLR2, TLR4 and MR mRNA expression in PBMCs was higher in patients with sarcoidosis than in healthy subjects (6-fold, 11-fold, 18-fold, and 4-fold, respectively)." (PMID 27688795, 2016). "TLR2 stimulation by serum amyloid A can regulate granuloma formation in sarcoidosis independent of any direct infection of monocytes." (PMID 38165044, 2024). "Diving deeper into the specific immune drivers of fibrotic sarcoidosis, in our view, the strongest data point to two broad groups of cells, Th17 cells in the adaptive immune system and CCL-18-expressing innate immune cells, and possibly macrophages via the recognition of PAMPS with TLR2." (PMID 36543347, 2022). "In the context of sarcoidosis these results provide new puzzle pieces of the largely unknown pathogenesis of this disease suggesting a role of IL-26 in the activation of moDCs via TLR2 followed by the secretion of TNF-α, an important pathological player and therapeutical target in sarcoidosis." (PMID 33057074, 2020).
skin infection (14 papers, 2012 to 2025). An inflammatory process affecting the skin, caused by bacteria, viruses, parasites, or fungi. "Severe AD-associated infections have been linked to toll-like receptor 2 (TLR-2) polymorphisms, which increase susceptibility to skin infections by reducing IL-6 and IL-12, and T-cell immunity." (PMID 40438776, 2025). "To investigate whether these PRRs contributed to IL-1β production and neutrophil recruitment during a S. aureus skin infection in vivo, we inoculated wt mice and mice deficient in TLR2, NOD2 or FPR1 with S. aureus." (PMID 23209417, 2012). "The use of a novel TLR2/STING agonist adjuvant was shown to be particularly effective for targeting S. aureus skin infection and, furthermore, can be improved by the inhibition of IL-10." (PMID 38973612, 2024). "It has been reported that TLR2 signaling plays a role in host bacterial burden control at early time points during S. aureus skin infection." (PMID 36226943, 2022). "We also found that MRSA MVs can induce TLR2 expression in HaCaT cells, which implies a critical role for TLR2 signaling in skin infections." (PMID 36558763, 2022). "Since differences in bacterial loads were TLR2 independent, the metabolic fitness or other TLR2 independent mechanisms of Lpp are most likely prodominent in model of S. aureus skin infections." (PMID 33785850, 2021). "More recently, MG extract is shown to possess antibacterial activity against S. aureus and dramatically downregulate the expression of TH1 cytokines, namely TNF-α, IL-6, and IL-1β, via the TLR-2 pathway in a skin infection model of mice." (PMID 30959963, 2019). "The increased lesion sizes, higher bacterial burden and impaired IL-1β production in TLR2- and NOD2-deficient mice in response to S. aureus skin infection is consistent with previously published studies from our laboratory and others." (PMID 23209417, 2012). "Interestingly, mice respond to S. aureus skin infections by increasing their AFA production in a TLR2-dependent manner." (PMID 32999082, 2020). "Therefore, in addition to having higher in vivo bacterial burden, mice deficient in TLR2, NOD2 and FPR1 also had decreased IL-1β production and neutrophil recruitment during a S. aureus skin infection in vivo." (PMID 23209417, 2012). "Thus, we evaluated TLR2-, NOD2-, or FPR1-deficient mice in response to S. aureus skin infection and found that each of these mice had impaired IL-1β production and neutrophil recruitment after S. aureus skin infection." (PMID 23209417, 2012). "In addition, S. aureus-induced NET formation is strictly regulated and requires both TLR2 activation and complement protein C3, as TLR2- or C3-deficient mice were unable to release nuclear DNA or histones, nor perform TLR2 or C3a receptor stimulation alone during skin infections." (PMID 40005560, 2025).
staphylococcal infection (14 papers, 2006 to 2021). An infection caused by Staphylococcus. "A number of reports have documented that TLR2 plays a crucial role in the host response against S. aureus because knockout mice deficient in TLR2 are highly susceptible to staphylococcal infections." (PMID 26200352, 2015). "Interestingly, TLR2 deficit enhances the host’s susceptibility to staphylococcal infection, attenuates pro-inflammatory cytokine production, and results in high mortality." (PMID 24058538, 2013). "TLR2 recognizes Gram+ PAMPs like lipoprotein and peptidoglycan, and several studies have shown the importance of TLR2 in Staphylococcal infection." (PMID 34520397, 2021). "Direct activation of TLRs in neutrophils, specifically TLR2 in staphylococcal infections, downregulates the expression of chemokine receptor CXCR2 that keeps their recruitment to infectious foci." (PMID 29867945, 2018). "While the role of these pathways in staphylococcal infection have primarily been established in S. aureus, there is evidence that the cellular recognition receptor, Toll-like receptor 2 (TLR2), plays a significant role in S. epidermidis bloodstream infection." (PMID 29541068, 2018). "This study has demonstrated the novel finding that S. aureus infection most probably induces TLR2-dependent alternative activation of macrophages which contributes to persisting staphylococcal infection." (PMID 24341851, 2013). "The relevance of TLR2-driven immune responses during staphylococcal infections and more particularly neutrophil recruitment has been recently studied." (PMID 23316483, 2012). "We will also consider what is known about the contribution of TLR2 to the recruitment of neutrophils during staphylococcal infections." (PMID 23316483, 2012). "Although there is a consensus concerning the role of phagocyte TLR2, stimulated with staphylococcal ligands in vitro, reports on the role of lipoproteins in murine staphylococcal infections in vivo are more discordant." (PMID 23316483, 2012). "Neutrophils are an essential part of the immune response to staphylococcal infections, and in the second part of this review we will therefore describe the role of TLR2 in PMN recruitment in response to staphylococcal infections." (PMID 23316483, 2012). "In order to elucidate if and under which conditions TLR2 may be crucial in staphylococcal infections we compared different Gram-positive pathogens including several S. aureus strains for their capacity to stimulate TLR2." (PMID 27470911, 2016). "Thus, TLR2 has not only beneficial but also detrimental roles in host innate response to staphylococcal infections." (PMID 24058538, 2013). "Thus, TLR2 participates actively to neutrophil stimulation and recruitment during staphylococcal infections." (PMID 23316483, 2012). "However, the function of TLRs, and more particularly TLR2, during staphylococcal infections is still debated." (PMID 23316483, 2012).
cervical cancer (13 papers, 2013 to 2024). A primary or metastatic malignant neoplasm involving the cervix. "Additionally, a link between TLR2 (−196 to −174 del) and cervical cancer susceptibility, as well as HCC development in HCV patients, was reported." (PMID 39071840, 2024). "Their results showed that mutant alleles of TLR2 rs3775290, TLR4 rs7873784, and TLR9 rs352140 were associated with increased cervical cancer risk." (PMID 34837895, 2021). "For example, Tlr2, a gene that is known to be related to take a significant role in HPV associated cervical cancer, was also over expressed exclusively in E6/E7+E2." (PMID 31881980, 2019). "In a study conducted in the United States, TLR2 and TLR4 expression levels were found to be greater in cervical cancer and premalignant lesions than in normal controls." (PMID 39208235, 2024). "The expression of TLR2 and TLR4 immune receptors is higher in human cervical cancer than that of other TLRs." (PMID 39621646, 2024). "Secondly, we identify CD40, CD27, and TIM-3 to specifically discriminate cervical cancer from other groups and CD40, CD28, and TLR2 to positively correlate to genital inflammation." (PMID 32802959, 2020). "Elevated levels of CD40, HVEM, PD-1, and TIM-3 connected cervical carcinoma to genital inflammation, whereas LAG-3 connected carcinoma to dysbiotic microbiota and TLR2 bridged genital inflammation and Lactobacillus dominance." (PMID 32802959, 2020).
chlamydial infection (13 papers, 2006 to 2025). "Interestingly, it sometimes happens, even in chlamydial infection, that in the presence of TLR2 or TLR4 deficiency in macrophages, there may be a decrease in TNF-α levels." (PMID 40647668, 2025). "TLR2 is involved in the host immune defense mechanism towards chlamydial infection and may have a potential role in the induction of chronic inflammatory sequelae as oviduct pathology was attenuated in mice knockout for TLR2." (PMID 36870960, 2023). "Deficiency of TLR2 or TLR4 in macrophages significantly reduces TNF-α levels during chlamydial infection,while deficiency of TLR3 in epithelial cells increases its levels at the early stage of chlamydial infection." (PMID 34093528, 2021). "Both intracellular TLR2 and the NOD1 intracellular pattern recognition receptor, which detects specific motifs in bacterial peptidoglycan, have been implicated in the induction of a CXCL8 response to chlamydial infection." (PMID 27002636, 2016). "In addition, data from in vivo infection models demonstrated that TLR2 knockout mice had a more severe disease, as well as an intense and prolonged chlamydial infection, as compared to wild type mice, and TLR3 and STING played a key role in the activation of a multitude of inflammatory modulators." (PMID 32050567, 2020). "In addition to TLR2, the NOD1 intracellular pattern recognition receptor, which detects specific motifs in bacterial peptidoglycan, has also been implicated in the induction of a CXCL8 response to chlamydial infection." (PMID 25010668, 2014). "Most immunological studies, conducted primarily on mouse models, have shown that TLR2 and TLR4 activation and signalling strongly influence the elimination of chlamydial infection and the prevention of immunopathological sequelae." (PMID 39614880, 2024). "And the involvement of TLR2 and TLR4 in the initiation of immune cell activation and immunological response in chlamydial infections were demonstrated in several studies." (PMID 35693111, 2022). "During chlamydia infection TLRs found on immune cells particularly TLR2, TLR4 and TLR9 which are important in recognizing and sensing chlamydia, are highly expressed in the female genital tract where they mediate immune cell response to chlamydia." (PMID 31388084, 2019). "However, TLR2, and not TLR4 appears to be important for the initial signaling pathway for proinflammatory cytokine production during chlamydial infection." (PMID 16995947, 2006).
coronary artery disease (13 papers, 2012 to 2025). "TLR2 and TL4 are strongly implicated in atheroma development and progression, leading to coronary artery disease." (PMID 27795867, 2016). "TLR2 and TLR4 are expressed by macrophages, neutrophils, and dendritic cells and have been implicated in the development of coronary artery disease (CAD) through activation of NF-κB pathways." (PMID 27795867, 2016). "Both expression levels of TLR2 and CD14 were lowest in the normal group and were high in the population with coronary artery disease and acute coronary syndrome." (PMID 33574831, 2020). "It should be noted that monocyte TLR4, but not TLR2, is upregulated in ischemic heart disease patients with ‘reduced EF’." (PMID 26030867, 2015).
respiratory infection (13 papers, 2008 to 2024). "In an acute model of Mtb respiratory infection, TLR2-/- and TLR4-/- mice showed increased susceptibility during early stages of infection, while macrophages from these mutant mice displayed reduced induction of antibacterial activities upon Mtb infection." (PMID 23448601, 2013). "We investigated the role of TLR2 and 4 in the induction of immune responses to Chlamydia muridarum respiratory infection, in neonatal wild-type (Wt) or TLR2-deficient (−/−), 4−/− or 2/4−/− BALB/c mice." (PMID 22724018, 2012). "In particular, TLR2 plays a major role in promoting protective immunity against respiratory pathogens, and its upregulation could reduce susceptibility to further respiratory infections." (PMID 26335787, 2015). "To determine the role of TLR2 expression during respiratory infection with C. muridarum, we infected C57BL/6 and TLR2-deficient mice on the same background intranasally with a sublethal dose of bacteria (5×103 IFU per mouse), and monitored for weight loss and survival." (PMID 21695078, 2011). "Our present results show that Tlr5−/− mice are more susceptible to B. pseudomallei in a model of respiratory infection, in contrast to deficiency in Tlr2, which actually confers resistance, or Tlr4, which has no apparent effect on survival." (PMID 25232720, 2014). "Thus, our data suggests that TLR2 plays an important anti-inflammatory role in the lung during respiratory infection with Chlamydia." (PMID 21695078, 2011). "Thus, TLR2 plays a critical role in the ability of innate immunity to determine M. pulmonis numbers in the lung, and it is likely that early after respiratory infection that TLR2 recognition of M. pulmonis triggers initial cytokine responses of host cells." (PMID 20505832, 2010). "However, TLR2 recognition of viable M. pulmonis is most likely still important in the host's responses early after respiratory infection." (PMID 20505832, 2010). "However, our observations of enhanced cytokine production support their findings of reduced bacterial loads and improved survival in respiratory infection in TLR2-/- mice compared to wild type mice." (PMID 18691413, 2008). "Recent studies, also in adult mice, show that TLR2 is required to control inflammation but not C. muridarum respiratory infection (replication)." (PMID 22724018, 2012). "In conclusion, TB activate TLR2 pathway without inducing a relevant pro-inflammatory response and improve barrier function, leading to the concept that TB preserve epithelial homeostasis and could be used as strategy to prevent and to manage respiratory infection, exacerbations included." (PMID 38814518, 2024).